MET (MET proto-oncogene, receptor tyrosine kinase)
Diseases named in the same sentence as MET in open-access papers (continued):
Sharing a sentence is not in itself a finding about the gene and the disease.
infection (continued). "Infection of MET-depleted cells with wildtype L. monocytogenes resulted in a reduction in the number and size of aggregates associated with host cells after 2 h infection, compared to control cells in which MET had not been depleted." (PMID 39045131, 2024). "Therefore, to further investigate the interactions between aggregates and MET we used immunostaining to measure and manipulate the cell-surface MET expression in HeLa cells upon infection with wildtype Lm-dsRed and actA-ΔC-dsRed strains." (PMID 39045131, 2024). "Furthermore, a significant decrease in the Ly6G+ area at the site of infection was observed in mice treated with the c-MET inhibitor, correlating with the results obtained with mice genetically deficient in c-MET in their neutrophils." (PMID 35041723, 2022). "In addition, c-MET activation was required for the infection and survival of Plasmodium sporozoites in hepatocytes." (PMID 35041723, 2022). "To further explore the impact of infection on c-MET expression, we determined whether parasite internalisation induced c-MET surface expression in neutrophils harboring or not parasites." (PMID 35041723, 2022). "However, in vivo, following infection with a high dose of parasites, the impact of c-MET expression on ROS production by neutrophils is compensated by other local activating factors of neutrophils." (PMID 35041723, 2022). "The findings reported here that several additional human kinases such as c-MET and B-Raf are activated by infection raise the question of whether their inhibition would likewise impair parasite proliferation." (PMID 32782246, 2020). "This raises the testable hypothesis that GSK3a and RSK1 activity may be dependent on c-MET activation during infection." (PMID 33015142, 2020). "However, at the same time, inhibiting c-MET eliminated the promotive effects of rAd-HGF infection on hBMSC osteogenesis, indicating that c-MET also contributed to hBMSC differentiation." (PMID 29510550, 2018). "In our study, we uncovered a surprising difference in the role of MET signaling in LS infection." (PMID 29089541, 2017). "Module 2 focused on epithelial barrier function and growth factor signaling, identified EREG, FGFR2, and MET as central hubs, alongside AREG and HBEGF, which support epithelial repair and regeneration after infection-induced damage." (PMID 40634947, 2025). "In this study, the MOI-dependent effects of rAd-HGF infection for HGF expression on hBMSC proliferation and osteogenic differentiation have been explored, while the roles of c-MET-related signaling pathways are also investigated." (PMID 29510550, 2018). "Among the early infection markers, two networks (−log10p = 31 and −log10p = 15) centered on MYC and MET respectively were significant." (PMID 26214306, 2015). "The frequency of intracellular parasites present in neutrophils 20h post-L. mexicana-DsRed infection was analyzed by flow cytometry to determine if the parasite presence was impacted in absence of c-MET." (PMID 35041723, 2022). "In contrast, infection of DCs and macrophages did not induce significantly c-MET expression in vitro." (PMID 35041723, 2022). "Infection with the pri-miR-1-expressing virus silenced the validated miR-1 targets FOXP1 and MET." (PMID 33335978, 2020). "Moreover, we demonstrated that mechanisms responsible for BsAb-5 in CD166+ LCSCs included inducing c-MET degradation and inhibition of HGF-stimulated c-MET-Notch pathway by using AdHGF infection, nuclei location, and Western blot assays." (PMID 29187584, 2019). "As expected, on single -positive EGFR−/c-MET+ SK-Mel-23 cells, Ad5/3-DM but not Ad5/3-tE triggered a significant induction of cytokine secretion and activation marker expression compared to Ad5/3-ΔE3 infection." (PMID 41552759, 2026).
infection (continued). "Interestingly, c-MET is usually activated through the binding of the extracellular ligand hepatocyte growth factor, which was not present in the cell culture medium used in these experiments; how c-MET is activated during infection is intriguing and remains to be determined." (PMID 33015142, 2020).
digestive system tumors (10 papers, 2016 to 2025). "Alteration of the MET/ hepatocyte growth factor (HGF) pathway has been associated with more aggressive disease and poorer prognosis in different gastrointestinal neoplasms." (PMID 35834132, 2023). "In preclinical studies, AMF-26 was demonstrated to be effective against HER2-negative, MET-positive gastrointestinal tumors that are characterized by gene amplification of MET by downregulating its membrane expression." (PMID 37046746, 2023). "Several anti-HGF and anti-c-MET monoclonal antibodies direct against extracellular combination of c-MET and HGF have been developed for the inhibition of c-MET-mediated digestive system tumor." (PMID 30360560, 2018). "Similarly, as a MET inhibitor, Savolitinib has received NMPA approval for treating NSCLC, but for gastrointestinal tumors (mainly GC and PC), it remains in the phase I clinical stage exploring pharmacokinetic and related properties." (PMID 41361128, 2025).
CNS tumors (8 papers, 2008 to 2024). "MET fusions are the least frequently occurring RTK gene fusions with three oncogenic fusions described in pediatric CNS tumors: CLIP2-MET, TFG-MET and PTPRZ1-MET." (PMID 39409964, 2024). "In the three different MET fusions in pediatric CNS tumors, CLIP2-MET, TFG-MET, and PTPRZ1-MET, the kinase domain of MET is retained within the fusion (Online Resource 8)." (PMID 35169893, 2022). "This is the case of the antitumor activity not previously reported in patients with MET and FGFR1 fusion–positive CNS tumors." (PMID 37399010, 2023).
hematological malignancies (7 papers, 2013 to 2025). "While the role of HGF/c-MET axis activation has been extensively studied in solid tumors, its potential in hematological malignancies remains underexplored." (PMID 40520181, 2025). "Although studies on the activation of the c-MET receptor in hematological diseases are relatively limited, emerging evidence suggests that the interaction between c-MET and its HGF ligand may promote the expansion of the leukemic clones." (PMID 40520181, 2025). "Although studies referring to activation of the HGF/c-MET axis in hematological diseases are relatively a few, it appears that this interaction may, directly or indirectly, favor the expansion of the leukemic clone." (PMID 30642077, 2019). "Finally, a better comprehension of the complex cross-talk among leukemic cells, stromal cells, and immune cells within a structured model of culture should further clarify the potential role of HGF/c-MET axis in pathogenesis and progression of hematological disease." (PMID 30642077, 2019). "This brief overview outlines how upregulated c-MET expression on leukemic cells, and paracrine but also autocrine release of HGF, may create favorable conditions to the expansion of myeloid and lymphoid cells in hematological diseases." (PMID 30642077, 2019).
lung (7 papers, 2004 to 2021). "c-MET/HGF-R expression was found in 80% (12 of 15) of liver specimens isolated from resected lobes of colorectal liver metastatic patients and in all liver samples from benign tumor patients." (PMID 14960204, 2004). "Overall survival (OS) for Stage IV lung ADC at initial diagnosis were analyzed in patients with BRAF V600E or with undetected mutation (no driver mutation/fusion detected in BRAF, EGFR, KRAS, ALK, ROS1, RET, HER2, or MET genes)." (PMID 31234388, 2019). "We found that MET, EGFR and phosphorylated STAT3 proteins were decreased after LOC389641 knockdown in human lung AD cell lines." (PMID 33318313, 2020).
neurodevelopmental disorder (4 papers, 2016 to 2023). A behavioral and cognitive disorder with onset during the developmental period that involves impaired or aberrant development of intellectual, motor, or social functions. "Advances in multiplex in situ techniques will provide opportunities to more carefully characterize the coexpression of multiple members of the MET interactome, 11% of which have been associated with neurodevelopmental disorders, in discrete neocortical neuron subpopulations." (PMID 27595133, 2016). "This interaction may have implications for neurodevelopmental disorders and neurodegenerative diseases, providing potential targets for therapeutic interventions aimed at modulating the NMDAR/MET interaction." (PMID 38201232, 2023).
blood cancers (3 papers, 2016 to 2025). "In blood cancers, nurse-like cells (NLCs) expressing c-MET exhibit aggressive characteristics." (PMID 40520181, 2025).
cardiovascular diseases (3 papers, 2018 to 2025). "Given the clinical relevance of atrial thrombus formation as a frequent complication in cardiovascular disease, we further examined whether AngIV affects expression of HGF or c-MET and whether it regulated c-MET phosphorylation in atria of mice after 30 days of AngIV administration." (PMID 40028176, 2025).
neurodegenerative disease (3 papers, 2021 to 2024). A disorder of the central nervous system characterized by gradual and progressive loss of neural tissue and neurologic function. "All these MET agonists created by different strategies are expected to augment the therapeutic armamentarium for brain repair and neurological and neurodegenerative diseases." (PMID 34179015, 2021).
digestive system cancer (2 papers, 2018 to 2020). A primary or metastatic malignant neoplasm involving any part of the digestive system. "In the current review, we will discuss recent findings about inhibitors of HGF/c-MET signaling in treating digestive system cancers, and how miRNAs regulate digestive system cancers via mediating HGF/c-MET pathway." (PMID 30360560, 2018). "Multiple inhibitors of HGF/c-MET signaling have shown antitumor activity in the preclinical phase of digestive system cancers." (PMID 30360560, 2018). "Several publications have reported that several miRNAs inhibit digestive system cancer progression through targeting c-MET." (PMID 30360560, 2018). "In the current review, the physiological and pathological mechanisms of the aberrant HGF/c-MET in digestive system cancers have been described." (PMID 30360560, 2018). "c-MET inhibitors were diverse for digestive system cancers, however, safety and efficacy have become the main problems in clinical stage studies." (PMID 30360560, 2018). "In the future, the miRNAs-HGF/c-MET axis could serve as a potential target for digestive system cancer treatment." (PMID 30360560, 2018). "However, the clinical efficacy of some inhibitors is limited, and some novel HGF/c-MET signaling inhibitors or medication strategies are being developed for digestive system cancers." (PMID 30360560, 2018). "Specifically, the new therapies using c-MET inhibitors have been highlighted and some special miRNAs that mediate c-MET in partial digestive system cancers have been summarized." (PMID 30360560, 2018). "The HGF/c-MET pathway is active in the development of digestive system cancers, indicating that inhibition of HGF/c-MET signaling may have therapeutic potential." (PMID 30360560, 2018). "The observed efficacy and adverse events of some c-MET inhibitors were not very suitable for treating digestive system cancers." (PMID 30360560, 2018).
skeletal disease (1 paper, 2017). "Cabozantinib, a c-MET and vascular endothelial growth factor receptor 2 inhibitor, demonstrated to prolong progression free survival and improve skeletal disease-related endpoints in castration-resistant prostate cancer and in metastatic renal carcinoma." (PMID 28223547, 2017).
MET also shares sentences with these, for which no sentence is quoted: multiple myeloma (17 papers); Cirrhosis (12); colorectal adenoma (7); Hypertension (6); multiple sclerosis (6); prostate adenocarcinoma (6); chronic pancreatitis (5); fibrosis (5); myocardial infarction (5); papillary carcinoma (5); acute liver failure (4); Arthritis (4); atherosclerosis (4); cervical squamous cell carcinoma (4); hepatoblastoma (4); influenza (4); metabolic disease (4); metastatic prostate carcinoma (4); acute lymphoblastic leukemia (3); acute myocardial infarction (3); alveolar rhabdomyosarcoma (3); autoimmune disease (3); breast adenocarcinoma (3); chronic obstructive pulmonary disease (3); emphysema (3); endothelial dysfunction (3); inflammatory breast carcinoma (3); invasive ductal carcinoma (3); osteoarthritis (3); ovarian clear cell adenocarcinoma (3).
A further 232 diseases each share a sentence with MET in 3 papers or fewer.